ADAM17 (ADAM metallopeptidase domain 17)
Diseases named in the same sentence as ADAM17 in open-access papers (continued):
Sharing a sentence is not in itself a finding about the gene and the disease.
hypotrichosis (1 paper, 2024). A congenital condition, usually due to genetic aberrations, that is characterized by a lack of hair growth on the head and/or body. "Here, we discovered a dominant variant in adisintegrin and ametalloproteinase domain 17 (ADAM17) gene caused hypotrichosis with woolly hair." (PMID 38771644, 2024). "In this study, we identified a subtype of congenital hypotrichosis with woolly hair that we designated ADWH3, caused by a heterozygous mutation in ADAM17." (PMID 38771644, 2024).
ischemia reperfusion injury (1 paper, 2022). Adverse functional, metabolic, or structural changes in ischemic tissues resulting from the restoration of blood flow to the tissue (reperfusion), including swelling; hemorrhage; necrosis; and damage from free radicals. "Furthermore, enzymes associated with active RA, such as ADAM17 (ADAM metallopeptidase domain 17), are known to cleave MerTK from the cell surface, and to promote tissue inflammation by limiting production of pro-resolving mediators in other diseases such as ischemia-reperfusion injury." (PMID 35455985, 2022).
ischemic stroke (1 paper, 2017). A stroke disorder caused by obstruction of blood flow to the brain, due to thrombotic (local blood clot formation) or embolic (due to a blood clot or other material traveling from another site) event. "Collectively, these observations demonstrate that soluble factors present in peripheral circulation following ischemic stroke have the capacity to trigger ADAM17-dependant sCD163 shedding from peripheral blood monocytes, however likely not from neutrophils." (PMID 29021532, 2017). "Transcriptional levels of both ADAM17 and sCD163 were significantly elevated in the whole blood of ischemic stroke patients relative to that of both control groups independently of age." (PMID 29021532, 2017). "Expectedly, the increase in monocytic sCD163 production which we observed upon stimulation with ischemic stroke serum was largely ablated by treatment with Marimastat, inferring that it was generated via the canonical sCD163 pathway involving ADAM17." (PMID 29021532, 2017). "Protein assays supported these observations, as ischemic stroke patients displayed significantly heightened cellular ADAM17 activity in peripheral blood total hemocyte fractions, as well as significantly elevated plasma levels of sCD163, once again in an age-independent fashion." (PMID 29021532, 2017).
kidney cancer (1 paper, 2014). Primary or metastatic malignant neoplasm involving the kidney. "In summary, we report, in kidney cancer, that MUC1 is involved in cancer progression and sheddases ADAM10, ADAM17 and gamma-secretase are necessary for MUC1-C nuclear location and in increase of invasiveness." (PMID 24504508, 2014).
Listeria monocytogenes infection (1 paper, 2017). "To test the role of ADAM17 in the generation and function of a T-cell response in vivo, we applied the Listeria monocytogenes infection model." (PMID 28877252, 2017). "In conclusion, our study indicates that ADAM17 is either not required in T cells under homoeostatic conditions and for control of listeria infection or can be effectively compensated by other mechanisms." (PMID 28877252, 2017).
liver cirrhosis (1 paper, 2020). "Consistent with a pro-fibrotic role of ADAM17, substrates of ADAM17 are elevated in the serum of patients suffering from liver cirrhosis." (PMID 32698506, 2020).
liver diseases (1 paper, 2021). "Given our current findings that ADAM17 plays an important role in regulating liver injury and sickness behavior development in BDL mice, we next delineated changes in hepatic ADAM17 expression in the setting of two important cholestatic liver diseases in patients; PBC and PSC." (PMID 35095853, 2021).
low grade glioma (1 paper, 2023). A grade I or grade II glioma arising from the central nervous system. "In addition, based on TCGA data obtained through cBioPortal, we discovered that ADAM17 transcript levels were markedly elevated in GBM compared with those in low-grade glioma." (PMID 37175410, 2023).
macular degeneration (1 paper, 2022). Loss of vision in the central portion of the retina (macula), secondary to retinal degeneration. "ADAM17 induces the release of soluble VLDLR (sVLDLR), which inhibits the Wnt pathway and leads to macular degeneration in eye tissue, whereas the shedding of sVLDLR is blocked by selective ADAM17 inhibitors." (PMID 36466812, 2022).
malaria (1 paper, 2016). Malaria is a serious and sometimes fatal disease caused by a parasite that commonly infects a certain type of mosquito which feeds on humans. "An increased amount of cytokines released by ADAM17 and endothelial activation with associated increase in plasma levels of Ang2 have been reported in malaria patients." (PMID 27784899, 2016). "To determine whether ADAM17 plasma levels were associated with clinical malaria, we measured ADAM17 plasma levels by ELISA." (PMID 27784899, 2016). "During malaria convalescence, ADAM17 plasma levels markedly declined to levels similar to those of asymptomatic malaria-infected children." (PMID 27784899, 2016). "Little is known about ADAM17 in malaria, but the cleavage of host receptors specifically utilized by IEs in severe malaria patients and cytokines, such as TNFα, which are increased in SM, suggests ADAM17 plays a role in malaria pathogenesis." (PMID 27784899, 2016). "The median ADAM17 level for the non-malaria patient group was 2,418 pg/ml, similar to UM and SM patients." (PMID 27784899, 2016). "Plasma levels of ADAM17 during acute malaria were compared to plasma levels during recovery in samples collected at admission from hospitalized children and from the same children between 2 to 12 weeks after admission." (PMID 27784899, 2016). "We found ADAM17 plasma levels elevated in hospitalized children with malaria compared with children with asymptomatic malaria infections." (PMID 27784899, 2016). "The plasma levels of ADAM17 decreased during recovery after an acute malaria episode." (PMID 27784899, 2016). "Thus, ADAM17 may influence availability of host receptors utilized by IE in malaria." (PMID 27784899, 2016). "This suggests that PfEMP1 expression and ADAM17 levels in the plasma are not directly affecting each other during malaria." (PMID 27784899, 2016). "Ang2 levels, unlike ADAM17, correlated with markers of disease severity, such as Blantyre coma score, Hb- and lactate levels in children hospitalized with malaria." (PMID 27784899, 2016).
malignant glioma (1 paper, 2014). A grade III or grade IV glioma arising from the central nervous system. "ii) ADAM17 expression was significantly associated with malignant gliomas." (PMID 25364437, 2014).
mantle cell lymphoma (1 paper, 2012). Mantle cell lymphoma is a rare form of malignant non-Hodgkin lymphoma affecting B lymphocytes in the lymph nodes in a region called the ``mantle zone''. "This may be ADAM10: ADAM10 has shown TNF-α sheddase activity in ADAM17-deficient murine fibroblasts and has been implicated in TNF-α production in mantle cell lymphoma." (PMID 22792380, 2012).
medulloblastoma (1 paper, 2020). A malignant, invasive embryonal neoplasm arising from the cerebellum. "Interestingly, ADAM17, encoding for an α-secretase, was discovered as a target of miR-218 in medulloblastoma." (PMID 32846925, 2020).
metastatic prostate carcinoma (1 paper, 2020). A carcinoma that arises from the prostate gland and has spread to other anatomic sites. "It would be evidential to target ADAM17 as a potential treatment strategy for the metastatic prostate cancer." (PMID 33204367, 2020).
neuropathic pain (1 paper, 2022). Chronic pain caused by damage to nerve fibers. "Thus, our study identifies ADAM17 as a key protease required for proteolytic maturation of α2δ-1 and α2δ-3, and thus a potential drug target in neuropathic pain." (PMID 35462614, 2022).
pemphigus (1 paper, 2022). Pemphigus is a group of rare autoimmune diseases that cause blistering of the skin and mucous membranes (mouth, nose, throat, eyes, and genitals).This conditioncan occur at any age, but often strikes people in middle or older age. "We addressed the role of the sheddases ADAM10 and ADAM17 in both keratinocyte adhesion and loss of cell adhesion in pemphigus in human keratinocytes." (PMID 35844545, 2022). "Sheddases ADAM10 and ADAM17 are involved in the turnover of the desmosomal cadherin Dsg2 and ADAM10 has been shown to contribute to acantholysis in a murine pemphigus model." (PMID 35844545, 2022).
periodontal disease (1 paper, 2022). "We previously reported that the severity of periodontal disease may be associated with the expression of the ADAM17 gene in the human buccal mucosal epithelium, and that ADAM17 is strongly expressed in the epithelium of gingival tissues and regulates the production of TNF-α from oral keratinocytes." (PMID 35200250, 2022). "In our previous study, the mRNA levels of ADAM17, which is related to the production of TNF-α, sTNF-R1, and sTNF-R2, were shown to be higher in the oral buccal mucosal epithelium according to the severity of periodontal diseases." (PMID 35200250, 2022).
preeclampsia (1 paper, 2023). Preeclampsia is a hypertensive disorder of pregnancy that is characterized by new-onset hypertension with proteinuria presenting after 20 weeks of gestation, and depending on mild or severe forms may initially present with severe headache, visual disturbances, and hyperreflexia. "They determined whether hypoxia/oxidative stress, an underlying pathophysiology of preeclampsia, would modulate ADAM17 expression and subsequently induce TNF-α production in placental trophoblasts." (PMID 37374349, 2023). "All placentas of pregnant women with preeclampsia with and without severe features for ADAM17 showed high expression." (PMID 37374349, 2023).
proliferative diabetic retinopathy (1 paper, 2020). Advanced retinopathy due to diabetes mellitus characterized by the formation of new vessels in the retina. "We investigated the involvement of these chemokine pathways and their processing metalloproteinases ADAM10 and ADAM17 in the pathophysiology of proliferative diabetic retinopathy (PDR)." (PMID 33552057, 2020). "Comparisons of vascular endothelial growth factor (VEGF), CXCL16, CX3CL1, ADAM10 and ADAM17 levels in proliferative diabetic retinopathy (PDR) patients with or without active neovascularization and nondiabetic patients with rhegmatogenous retinal detachment (RD)." (PMID 33552057, 2020).
retinal degeneration (1 paper, 2020). Degeneration of the retina. "This correlates well with the complete rescue of retinal degeneration seen in dark‐reared flies, suggesting that peroxidated lipids are indeed the major cause of cell death in ADAM17−/− mutants." (PMID 32715522, 2020). "We therefore asked whether the retinal degeneration caused by glial ADAM17 loss also depends on ROS." (PMID 32715522, 2020). "The combination of lipid accumulation and elevated ROS in ADAM17−/− mutants suggested that toxic peroxidated lipids might be contributing to retinal degeneration." (PMID 32715522, 2020).
retinal ischemia (1 paper, 2020). A ischemic disease that involves the retina. "Importantly, we demonstrated that inactivation of ADAM17 activity in the endothelium also provides a significant protection against neuronal and vascular damage associated with retinal ischemia-reperfusion." (PMID 32751103, 2020). "Since activation of ADAM17 was clearly linked to vascular pathologies as well as inflammatory and neurodegenerative conditions, we were interested in determining whether ADAM17 is involved in neuronal and vascular damage associated with retinal ischemia." (PMID 32751103, 2020). "The obtained results provide evidence that endothelial ADAM17 is an important contributor to IR-induced neurovascular damage in the retina and suggest that interventions directed at regulating ADAM17 activity can be beneficial for alleviating the consequences of retinal ischemia." (PMID 32751103, 2020).
rhinitis (1 paper, 2022). An inflammation of the mucous membrane lining the nose, usually associated with nasal discharge. "Here, we investigated the role of ADAM17 in the human respiratory tract and found that its mRNA or protein levels were markedly elevated in lung tissue, rhinitis and bronchus." (PMID 35720350, 2022).
subarachnoid hemorrhage (1 paper, 2023). A serious neurological disorder characterized by intracranial hemorrhage into the subarachnoid space. "This expression partially correlated with MC iron accumulation, pro-inflammatory activation status as signified by HLA-DR expression, and expression of ADAM17 in case of subarachnoid hemorrhage." (PMID 37715818, 2023).
synovial sarcoma (1 paper, 2018). "Therefore, like ADAM17-P729H, other mutations we identified solely in metastatic synovial sarcoma may also have the potential to serve as an entry point for unraveling the metastatic mechanisms of synovial sarcoma." (PMID 30627328, 2018).
thalassemia (1 paper, 2018). An inherited blood disorder characterized by a decreased synthesis of one of the polypeptide chains that form hemoglobin. "Expression of ADAM17 and CD163 was increased (p < 0.05) in the hepatic tissue (cytoplasmic) and macrophages (sinusoidal spaces) in thalassemia patient’s liver tissue." (PMID 29980709, 2018).
Thrombocytopenia (1 paper, 2022). A reduction in the number of circulating thrombocytes. "The results indicate that ADAM17 is important in thrombopoiesis, and low expression of ADAM17 is possibly related to the observed thrombocytopenia in pediatric ITP." (PMID 35354403, 2022). "The fetus of ADAM17 Zn△/ Zn△ mice exhibited severe thrombocytopenia with bleeding spots in head, neck and abdomen." (PMID 35354403, 2022).
uterine carcinosarcoma (1 paper, 2022). A usually aggressive malignant neoplasm arising from the uterine corpus and less often the cervix. "In this study, ADAM17 was found to be expressed in 57 cases of uterine carcinosarcoma with the highest mutation frequency (10.53%), while it was barely expressed in 511 cases of kidney renal clear cell carcinoma with a mutation rate of 0.39%." (PMID 36558177, 2022).
xanthoma (1 paper, 2014). A non-neoplastic disorder characterized by a localized collection of histiocytes containing lipid. "This ‘xanthoma inflammatory profile’ might have resulted, at least in part, from increased expression and subsequent shedding of the membrane protein ADAM17." (PMID 24428816, 2014).
tumor (275 papers, 2005 to 2026). "A disintegrin and metalloprotease 17 (ADAM17), another protein associated with chemoresistance, enhances tumor cell proliferation and survival via the epidermal growth factor receptor (EGFR) pathway by cleaving various ligands such as amphiregulin (AREG)." (PMID 40757000, 2025). "Loss of FMR1 hinders m6A‐dependent decay of ADAM17 mRNA, resulting in ADAM17 accumulation in tumor exosomes and enhanced angiogenesis." (PMID 41058008, 2025). "Surface expression of CD16 is regulated by a disintegrin and metalloprotease 17 (ADAM17), which acts as a regulatory checkpoint by causing ectodomain shedding and NK cell detachment from the tumor cell." (PMID 39339180, 2024). "Transfer of ADAM17 deficient CD8+ T cells significantly slowed the tumor growth and improved the survival rate in mice compared to mice that received no T cells or WT T cells." (PMID 38918390, 2024). "To further explore their function in mediating the enhanced anti-tumor immunity of ADAM17 deficient CD8+ T cells, we examined their expression in WT and ADAM17 deficient CD8+ TILs in the ACT tumor model." (PMID 38918390, 2024). "KRAS-G12 mutants in tumour cells harbouring iRhom2 with TOC mutations further enhance constitutive ADAM17-mediated shedding." (PMID 38409522, 2024). "High ADAM17 expression was linked to poor tumour/node (T/N) stage and alpha fetoprotein (AFP) levels." (PMID 38069391, 2023). "Tumour volume was also reduced in tumours derived from ADAM17‐deficient FGFR2‐mutant EC cells (MFE280A17−/−, MFE296A17−/−, AN3CAA17−/−), further corroborating that ADAM17 activity is critical for tumour growth in FGFR2‐mutant EC cells." (PMID 37165578, 2023). "Numerous studies have confirmed that the shedding activity of ADAM17 is enhanced in many tumours, causing ADAM17 to be abnormally expressed." (PMID 38069391, 2023). "Pharmacological ADAM17 inhibition with TMI-5 resulted in additive inhibitory effects on tumor growth despite NOX1 deficiency in the mice." (PMID 38137406, 2023). "Boxplots showed that the increase in ADAM17 was associated with poor T and N stages of cancer, where T refers to the size and extent of the main tumour and N refers to the number of nearby lymph nodes affected." (PMID 38069391, 2023). "A similar decrease in HES1 and mTOR expressions was also observed in tumours derived from ADAM17‐deficient MFE296 cells." (PMID 37165578, 2023). "The metalloproteinase ADAM17 is associated with tumour formation and development; however, its significance in HCC is unclear." (PMID 38069391, 2023). "Actually, point mutations of the ADAM17 catalytic domain have been identified in tumor samples from cancer patients, which are associated with tumor-related dysfunction." (PMID 36558177, 2022). "In ADAM17flox/flox/Tie2-Cre mice, loss of endothelial ADAM17 inhibits chord formation and impedes ectopic injected tumor growth." (PMID 36466812, 2022). "This was documented by a positive correlation between ADAM17 and tumor-supporting macrophages in human patients with cancer and a causative link in mouse tumor models." (PMID 35998057, 2022). "Overexpression or enhanced activation of ADAM17 in tumor cells has been mostly associated with cancer initiation and progression." (PMID 36497350, 2022). "Taken together, Tspan8 subfamily members and ADAM17 are co-expressed and potentially functionally linked in different tumor cells." (PMID 36078095, 2022). "Our previous study revealed that ADAM17 overexpression in digestive tract malignancies was closely associated with tumor proliferation and metastasis." (PMID 34650435, 2021). "The tumor-associated metzincin metalloproteinases ADAM10 and ADAM17 can cleave the PD-L1 ectodomain from the surface of tumor cells and extracellular vesicles, thus producing a soluble form of PD-L1 (sPD-L1), which can induce CD8+ T cell apoptosis." (PMID 34945784, 2021).